PCSK9 (proprotein convertase subtilisin/kexin type 9)
Diseases named in the same sentence as PCSK9 in open-access papers (continued):
Sharing a sentence is not in itself a finding about the gene and the disease.
Hypercholesterolemia (continued). "Plasma PCSK9 levels in newly diagnosed PNS patients were markedly increased, and elevated PCSK9 abundance was positively correlated with elevated serum TC and LDL-C levels, suggesting that PCSK9 may emerge as a novel therapeutic target in NS-associated hypercholesterolemia." (PMID 32349585, 2020). "In our study, hypermethylation of promoters of key genes regulating cholesterol metabolism such as PCSK9, LRP1, ABCG1, ANGPTL4, SREBF1 and NR1H2, were found in obese patients with hypercholesterolemia." (PMID 33028190, 2020). "Currently, two PCSK9 inhibitors, RepathaTM and Praluent®, are approved for their clinical use to prevent degradation of the LDL receptor by PCSK9 and reducing hypercholesterolemia." (PMID 32587953, 2020). "Evolocumab and Alirocumab are fully humanized MABs that inhibit PCSK9 and were approved by the FDA in 2015 for treatment of hypercholesterolemia in combination with statins." (PMID 33076542, 2020). "Nonetheless, the association of the C679X variant with low fasting glucose in young participants that have no risk factors for diabetes, suggests that the PCSK9 inhibitor drugs which mimic these variants might even confer protection against both diabetes and hypercholesterolemia." (PMID 30899674, 2019). "For an endogenous gene target for in vivo studies, we selected Pcsk9, a regulator of LDL cholesterol levels targeted for repression in therapies for familial hypercholesterolemia." (PMID 29700298, 2018). "To conclude, PCSK9-mAb contributes to the decreased level of LDL-C and other lipids in familial hypercholesterolemia and statin-intolerant patients with satisfactory safety and tolerability." (PMID 28331223, 2017). "Higher levels of PCSK9 decrease the number of hepatic LDL receptors and can produce hypercholesterolemia." (PMID 25136459, 2014). "PCSK9, which interacts with the LDL receptor, is a promising therapeutic target for hypercholesterolemia and coronary artery disease." (PMID 23997648, 2013). "In 2012, a randomized control trial was published that a monoclonal antibody to PCSK9 significantly reduced LDL cholesterol levels in healthy volunteers and in subjects with hypercholesterolemia." (PMID 23696745, 2013). "Overexpression of wild-type Pcsk9 gene in mice results in reduced number of LDL-R and hypercholesterolemia." (PMID 17971861, 2007). "Proprotein convertase subtilisin/kexin type 9 (PCSK9) inhibitors, such as alirocumab and evolocumab, effectively reduce LDL-C levels, improve cardiovascular outcomes, and are well tolerated in the treatment of heterozygous familial hypercholesterolemia (HeFH)." (PMID 42178619, 2026).
Hypercholesterolemia (continued). "Specifically, male C57BL/6J mice were injected i.p. with a single dose of an adeno-associated virus (AAV) vector expressing the mouse D377Y gain-of-function proprotein convertase subtilisin/kexin type 9 (PCSK9), which resulted in sustained hypercholesterolemia." (PMID 39846252, 2025). "We also wish to note that the knockdown experiment with Pcsk9 and Bhlhe40 in SNP-bearing atherogenic mice blunted but did not completely remove the SNP effect on hypercholesterolemia and plaques." (PMID 40591411, 2025). "This simply means that PCSK9 inhibitors are very useful for patients with hypercholesterolemia, but do not tolerate statins." (PMID 40110272, 2025). "By specifically targeting and silencing mRNA of key genes, such as proprotein convertase subtilisin/kexin type 9 (PCSK9), involved in lipid metabolism, siRNA can achieve precise reductions in low-density lipoprotein (LDL) levels, effectively addressing hypercholesterolemia at a molecular level." (PMID 40093884, 2025). "Evolocumab and Alirocumab are presently the only two fully human PCSK9-targeting mAbs approved by the US Food and Drug Administration (FDA) and the European Medicines Agency (EMA) for the clinical treatment of hypercholesterolemia thanks to their potency, tolerability, and low immunogenicity." (PMID 39769398, 2024). "This was achieved through improvements in metabolic parameters, including CD36/liver X receptor α (LXRα)/sterol regulatory element-binding protein 1c (SREBP1c), proprotein convertase subtilsin/kexin type 9 (PCSK-9), and HMGCR, ultimately ameliorating HFD-induced hypercholesterolemia and obesity." (PMID 39519447, 2024). "Two groups were administered an adeno-associated virus encoding for the gain of function of proprotein convertase subtilisin/kexin type 9 (PCSK9) and placed on a high-fat diet (HFD) with 1.25% cholesterol added for 18 weeks in order to induce a prolonged state of hypercholesterolemia." (PMID 39790566, 2024). "Conditional deletion of Ccl2 in SMCs does not inhibit the development of atherosclerosis in mice with PCSK9-induced hypercholesterolemia." (PMID 38234375, 2024). "A recent clinical study showed that anti-inflammatory changes in monocyte phenotype with PCSK9 antibodies were not accompanied by a CRP reduction in patients with familial hypercholesterolemia." (PMID 39149582, 2024). "Inclisiran treatment did not reduce LDL-C levels in patients with homozygous familial hypercholesterolemia despite substantial lowering of PCSK9 levels." (PMID 37850379, 2024). "Previous studies have shown that the overexpression or underexpression of PCSK9 has crucial effects not only on circulating PCSK9 and LDL-C levels but also on cardiovascular diseases such as familial hypercholesterolemia (FH), metabolic syndrome, and coronary atherosclerotic heart disease (CHD)." (PMID 39736777, 2024). "mPCS1 targets the murine Pcsk9 (Proprotein convertase subtilisin kexin 9) mRNA, a well-known hypercholesterolemia target, but does not cover its human ortholog." (PMID 38042877, 2023).
Hypercholesterolemia (continued). "This approach examined whether there was a reverse causal relationship between urinary stones and circulating lipids (TG, LDL-C, HDL-C, APOA, APOB, and Pure hypercholesterolaemia) along with lipid-lowering drugs (HMGCR inhibitors and PCSK9 inhibitors)." (PMID 38107516, 2023). "The production of PCSK9 and Ox-LDL is increased in subjects with hypercholesterolemia." (PMID 37511498, 2023). "Our analysis identified four colocalized genes, CELSR2, PCSK9, LPA, and APOE, that are involved in lipid metabolism and may contribute to the development of both Pure hypercholesterolaemia and IHD." (PMID 38144368, 2023). "Anti-PCSK9 therapies have gained prominence in the treatment of hypercholesterolemia, and no serious adverse events have been observed from laboratory to clinical application." (PMID 37466835, 2023). "All studies have shown that PCSK9 mAbs (evolocumab or alirocumab) with or without statin therapy significantly reduce LDLc in patients with hypercholesterolemia and heterozygous familial hypercholesterolemia." (PMID 38093957, 2023). "A parabiotic experiment joining wild-type and PCSK9-overexpressing mice showed decreased LDL-R in the livers of the wild-type mice, making clear that the secreted form could induce hypercholesterolemia by inhibiting the LDL-R." (PMID 39086674, 2023). "PCSK9-Il1a-/- mice, but not PCSK9-Nlrp3-/- or PCSK9-Il1b-/- mice, are protected from atherosclerosis after induction of hypercholesterolemia independent of circulating cytokines." (PMID 37701434, 2023). "Taken together, PCSK9 inhibitors are recommended as additional or alternative therapy in patients with complete statin intolerance ASCVD and familial hypercholesterolemia (FH) with persistent hypercholesterolemia." (PMID 35371605, 2022). "Familial hypercholesterolemia and coronary artery plaques grow faster in transgenic Ossabaw mutant pigs, obtained by the transposition of chimpanzee’s DNA, expressing D374Y gain-of-function (GOF) PCSK9 genes." (PMID 36005422, 2022). "The p.Leu167del variant is known to cause hypercholesterolemia in 3.1% of ADH subjects without LDL, APOB, and PCSK9 mutations in Spain and a French patient among a cohort of 229 ADH subjects." (PMID 35628605, 2022). "BMS-962476, as an effective PCSK9 inhibitor, may have the potential to treat LDL in patients with hypercholesterolemia in the treatment of cardiovascular diseases." (PMID 36230934, 2022). "In patients with familial hypercholesterolemia intolerant to statin treatment with either PCSK9 inhibitor did not decrease D-dimer or fibrinogen, which is one of the most robust clinical markers for decreased thrombogenicity." (PMID 35806908, 2022). "To study whether PCSK9- and HFD-driven hypercholesterolemia alter coagulation parameters, we sampled blood from mice injected with either mPCSK9-AAV or control AAV and fed with either HFD or the standard diet 21 days post-injection." (PMID 34631822, 2021). "No similar therapeutic for hypercholesterolemia treatment has entered clinical trials yet, although two monoclonal antibodies to PCSK9 for passive immunotherapy have received market authorization." (PMID 33969434, 2021).
Hypercholesterolemia (continued). "The most advanced treatment is silencing of proprotein convertase subtilisin/kexin type 9 (PCSK9) with a drug called inclisiran, which has been approved for the treatment of hypercholesterolemia in late 2020, and results in a robust decrease in plasma cholesterol levels." (PMID 34146172, 2021). "Although their mild correlation was similarly observed in previous studies on patients with hypercholesterolemia under LLT, PCSK9 variants were not examined in these studies." (PMID 34652028, 2021). "Since enhanced platelet activation and secretion—especially in hypercholesterolemia—is well documented in patients with CAD, we hypothesized that platelets contribute to PCSK9 activity and thus the regulation of LDL plasma levels." (PMID 34681838, 2021). "Hypercholesterolemia has profound negative effect on cardioprotection and PCSK9 has emerged as a therapeutic target for reducing plasma LDL-C." (PMID 33262707, 2020). "In patients with familial hypercholesterolemia without cardiovascular disease, PCSK9 inhibitors can be considered if LDLc is higher than 200 mg/dL, or even lower, 175 mg/dL, if there are additional severity factors." (PMID 32375792, 2020). "Our study demonstrates that therapy with the PCSK9 inhibitors evolocumab and alirocumab lead to a significant reduction of LDL Cholesterol in heart transplantation recipients with hypercholesterolemia and therapeutic failure of statin regimens or statin intolerance." (PMID 30650126, 2019). "Circulating PCSK9 binds to the LDL receptor and diverts it to lysosomes for degradation, thereby leading to decreased LDL receptor abundance at the hepatocyte cell surface, decreased LDL clearance, and hypercholesterolemia." (PMID 30251625, 2018). "A large number of trials have shown robust reduction of LDL-C plasma level with the use of PCSK9 inhibitors as a monotherapy or in combination with statins in familial and nonfamilial forms of hypercholesterolemia." (PMID 29770231, 2018). "The rate of heterozygous familial hypercholesterolemia (HeFH) was significantly lower in the no-statin-no-PCSK9 group." (PMID 29951223, 2018). "The protein expression of PCSK9 was significantly increased by maternal hypercholesterolemia compared to control group with no significantly change of mRNA expression in human term placenta." (PMID 28199412, 2017).
Hypercholesterolemia (continued). "PCSK9 inhibitors, MTP inhibitors, antisense oligonucleotide against apolipoprotein B, adenosine Triphosphate Citrate Lyase Inhibitors are experimental and sometimes promising new classes of drugs for the treatment of hypercholesterolemia." (PMID 28793863, 2017). "The European Medicines Agency has approved the use of the PCSK9 inhibitors, evolocumab and alirocumab, in adults with heterozygous familial or the non-familial form of primary hypercholesterolaemia or with mixed dyslipidaemia." (PMID 28124099, 2017). "PCSK9 inhibitors are registered in Europe for treatment in primary hypercholesterolemia (heterozygous familial and non-familial) or, as an adjunct to diet, in mixed dyslipidemia." (PMID 29209441, 2017). "Moreover, we explored a possible link between liver Pcsk9, Srebf-2 (SREBP-2 as a positive regulator of Pcsk9 gene expression) genes expression and hypercholesterolemia observed in rats with CRF." (PMID 26481479, 2016). "In summary, this study, the largest monotherapy trial using a PCSK9 inhibitor to date, showed that evolocumab significantly reduces LDL-C plasma levels compared with placebo or ezetimibe and is well tolerated in patients with hypercholesterolemia." (PMID 25470376, 2014). "Clinical studies have shown that the subcutaneous administration of a monoclonal antibody to PCSK9 reduced LDL levels in a dose-dependent manner in up to 61% in patients with familial or nonfamilial hypercholesterolemia." (PMID 23844374, 2013). "The therapeutic inhibition of PCSK9 through monoclonal antibodies or siRNA has proven effective in reducing LDL-C levels and the incidence of atherosclerosis, highlighting its potential as a target for treating hypercholesterolemia and possibly other liver-related pathologies." (PMID 40764605, 2025). "Although approximately 60% of patients in our cohort exhibited elevated LDL and total cholesterol levels, this is comparable to rates in the general German population of similar age50, suggesting that hypercholesterolemia alone does not explain the rise in PCSK9." (PMID 41271978, 2025). "With increasing hypercholesterolemia prevalence in East Asian adolescents, pharmacologic interventions (e.g., HMGCR inhibitors (statins) and PCSK9 inhibitors) may have to be considered although their longer-term safety in the general adolescent population is unclear." (PMID 37904165, 2023). "A second target patient population for VERVE-201 is refractory hypercholesterolemia, as occurs in patients with atherosclerotic cardiovascular disease who fail to achieve adequate LDL-C reduction to protect from recurrent events even after use of oral therapies and a PCSK9 inhibitor." (PMID 37188660, 2023).